WFDC2 (WAP four-disulfide core domain 2)
Diseases named in the same sentence as WFDC2 in open-access papers (continued):
Sharing a sentence is not in itself a finding about the gene and the disease.
respiratory disease (4 papers, 2019 to 2024). "To further understand the impact of WFDC2 deficiency, we analyzed saliva from healthy control individuals (n = 3), individuals with WFDC2 mutations (n = 3), and control individuals with respiratory disease (PCD, n = 2; CF, n = 2) by liquid chromatography with tandem mass spectrometry (LC-MS/MS)." (PMID 38626355, 2024). "Here, we present evidence that whey acidic protein (WAP) four-disulfide core domain protease inhibitor 2 (Wfdc2), a protease inhibitor previously unrecognized in respiratory disease, may be a causal factor in infant respiratory failure." (PMID 31562139, 2019). "We analyzed SLPI by WB and, consistent with LC-MS/MS analysis, observed variable (not significantly altered) expression among healthy control, WFDC2-mutant, and respiratory disease control groups." (PMID 38626355, 2024).
gynecologic neoplasms (3 papers, 2020 to 2025). "Finally, the glycoproteins MUC16 and WFDC2 are two proteins widely evaluated, since their high expression demonstrated either diagnostic and prognostic value in gynecological tumors." (PMID 32560580, 2020).
WFDC2 also shares sentences with these, for which no sentence is quoted: endometriosis (40 papers); benign ovarian tumors (28); chronic kidney disease (12); Ovarian cyst (11); serous carcinomas (11); Ascites (9); heart failure (9); renal failure (9); epithelial ovarian tumors (7); mucinous ovarian cancer (6); cervical cancer (5); chronic heart failure (5); endometrial atypical hyperplasia (5); gynecological diseases (5); Hypertension (5); metastatic tumors (5); mucinous tumors (5); ovarian endometriosis (5); endometrial adenocarcinoma (4); idiopathic pulmonary fibrosis (4); Myocardial fibrosis (4); ovarian clear cell cancer (4); systemic lupus erythematosus (4); transitional cell carcinoma (4); benign breast tumors (3); breast tumor (3); clear cell carcinoma (3); endometrial polyp (3); epithelial malignant ovarian tumors (3); fibroid (3).
A further 134 diseases each share a sentence with WFDC2 in 3 papers or fewer.